CD33 (CD33 molecule)
Diseases named in the same sentence as CD33 in open-access papers (continued):
Sharing a sentence is not in itself a finding about the gene and the disease.
myeloid leukemia (27 papers, 2006 to 2025). A clonal proliferation of myeloid cells and their precursors in the bone marrow, peripheral blood, and spleen. "We obtained cryopreserved bone marrow aspirates (BM) from healthy donors and AML patients and performed flow cytometry using a myeloid leukemia panel (CD45/CD34/CD117/CD33/CD13/HLA-DR)." (PMID 40269321, 2025). "With low 1:15 E:T ratio, CD33 CAR T cells co-cultured with myeloid leukemia cells, HL60CD33 and THP-1CD33, showed poorer anti-tumor capacity compared to Nalm6CD33." (PMID 38184596, 2024). "Changed target expression, before or during treatment, was associated with potentially worse outcomes in haematological malignancies, including myeloid leukaemia with low CD33 expression." (PMID 37631232, 2023). "Our interest in CD33+ NK cells was fueled by an observation made during the generation and expansion of CD33-specific CAR NK cells for therapy of myeloid leukemia." (PMID 35058934, 2021). "Due to this experiment and the high expression of CD33 in myeloid leukemia, there are currently many activities considering anti-CD33 CAR therapy." (PMID 30736352, 2019). "Cluster of differentiation antigen 33 (CD33, SIGLEC3) is overexpressed on leukemic blasts, as well as on myeloid leukemia initiating cells." (PMID 30524966, 2018). "In the present study, we characterized a dual-targeting T cell-recruiting triplebody 33-3-19 that was designed for the selective lysis of CD19/CD33 double-positive B/myeloid leukemia cells over CD19 single-positive normal cells." (PMID 26981773, 2016). "These CD33 specific aptamers were sufficient in receptor related binding and also demonstrated internalization after binding in CD33+ myeloid leukemia lines making aptamers an attractive vehicle for specific targeted toxin delivery." (PMID 27240402, 2016). "The combination of B lymphoid marker CD19 and myeloid marker CD33 is exclusively present on biphenotypic B/myeloid leukemia cells." (PMID 26981773, 2016). "In contrast to myeloid leukemia, this study showed that CD33 expression in all patients with APL was bright, CD13 expression was dim to bright, cMPO expression was dim to moderate, and CD117 expression was generally dim." (PMID 25045197, 2014). "In particular, CD33 (Siglec-3) is a definitive marker for myeloid leukemias." (PMID 38254780, 2024). "Siglecs have long been associated with cancer: CD22 and CD33 are specific markers for B-cell lymphoma and anti-CD22 and anti-CD33 antibody therapies have also been used in clinical trials of B-cell lymphoma and myeloid leukemia." (PMID 37207210, 2023). "An NKCE, known as NKG2CxIL-15xCD33, comprising an anti-NKG2C scFv and an anti-CD33 scFv, linked by a wild-type IL-15 in the middle, has demonstrated satisfactory NK cell activation, expansion, and cytotoxicity against CD33+ myeloid leukaemia cells both in vitro and in vivo in an NSG mouse model." (PMID 37638058, 2023). "If such stability engineering were combined with affinity engineering to further increase the “selectivity window”, then later-stage versions of 33-3-19 may become potent and clinically useful therapeutic agents for a selective targeting of CD19+ CD33+ B/myeloid leukemia cells." (PMID 26981773, 2016). "This gene set was heavily enriched with myeloid leukemia drivers (e.g., FLT3, RUNX1, CD33) and other tumor-promoting genes, providing a direct mechanistic link between eccDNA presence and the transcriptional dysregulation that fuels AML." (PMID 41278279, 2025). "Integrative analysis identified 570 genes upregulated at both the eccDNA and mRNA levels, including myeloid leukemia-related genes (e.g., FLT3, RUNX1, and CD33) and oncogenes." (PMID 41278279, 2025). "Several molecular targets expressed on myeloid leukemia cells, such as CD123 and CD33 but also NKG2DLs and CD7, are currently being explored in the CAR field and more efficient protocols for CAR-NK cell development are being established." (PMID 31681270, 2019).
myeloid leukemia (continued). "Third, integrative analysis identified 570 genes upregulated at both the eccDNA and mRNA levels, including myeloid leukemia drivers (FLT3, RUNX1, CD33) and oncogenes (MAP2K2/3, LINC00539), mirroring the “eccDNA–oncogene amplification” axis observed in solid tumors." (PMID 41278279, 2025). "To determine if the down-regulation of CD33, CD123, CLL-1 CAR applies to different myeloid leukemia cell lines other than U937, we also conducted the co-cultured experience using THP-1, MOLM-13 and HL60 myeloid leukemia cell lines with CAR T cells." (PMID 38184596, 2024).
acute lymphoblastic leukemia (24 papers, 2012 to 2025). Leukemia with an acute onset, characterized by the presence of lymphoblasts in the bone marrow and the peripheral blood. "CD33 is broadly expressed on various myeloid lineages and has gained therapeutic relevance as target on CD33-expressing myeloid and rare subsets of acute lymphoblastic leukemia." (PMID 35058934, 2021). "Following the success of blinatumomab, a CD19-targeted bispecific antibody for the treatment of acute lymphoblastic leukemia, clinical trials have investigated CD33-targeted bispecific antibodies for AML." (PMID 34203180, 2021). "One autologous therapy (NCT05662904) treats acute lymphoblastic leukemia (ALL) by inactivating the CD33 gene in the patient’s HSPCs to make them immune to the CD33-specific antibody-drug conjugate Gemtuzumab-ozogamicin (GO), allowing escalation of GO doses." (PMID 41476860, 2025). "The sensitivity of CD33+ AML cells or CD33-transduced acute lymphoblastic leukemia (ALL) cells to CC-96191 varied substantially." (PMID 38473239, 2024). "Most trials target relapsed or refractory (R/R) hematological cancers, such as acute lymphoblastic leukemia (ALL), NHL, and AML, with CD19 and CD33 being the most common target antigens." (PMID 40519903, 2025). "On September 17, 2017, the FDA approved the use of GO for patients newly diagnosed with CD33-positive acute lymphoblastic leukemia (ALL) and those who had relapsed or refractory CD33-positive AML based on results from three clinical trials (ALFA-0701, AML-19, and MyloFrance-1)." (PMID 36418786, 2022). "Flow cytometric analysis indicated that human AML MOLM13 cells overexpressed CD33 on their surface while acute lymphoblastic leukaemia CEM cells were negative for CD33." (PMID 35851970, 2022). "Anti-CD19 CAR T-cell therapy is FDA-approved for B-cell precursor acute lymphoblastic leukemia (B-ALL) and under investigation for the treatment of AML with antigen targets such as CD33 and CD123." (PMID 41226551, 2025). "Moreover, CD33 is also expressed abnormally in 10–20% of B- and T-lymphoblastic leukemias/lymphomas but not in the normal T cells." (PMID 36680011, 2023). "This is used in conjugation with antibodies targeting CD33 (gemtuzumab ozogamicin/Mylotarg) in AML, or CD22 (inotuzumab ozogamicin) in B-cell acute lymphoblastic leukemia (ALL)." (PMID 31434267, 2019). "Flow cytometry confirmed precursor B-cell acute lymphoblastic leukemia (B-ALL), with the blasts expressing CD123, CD73/86, CD9, CD34, TdT, HLA-DR, CD58, CD38, cCD22, sCD22, cCD79a, and CD19, along with partial expression of CD24 and aberrant CD33." (PMID 40718322, 2025).
lung carcinoma (21 papers, 2011 to 2024). "Moreover, the therapeutic response can be affected by several parameters, such as the mutational load of GATA3+ cells, FOXP3+ cells and CD33+ cells and the abundance of TILs in lung cancer or melanoma." (PMID 34221962, 2021). "The addition of tumor-derived CD33+ cells from colon and lung cancer patients significantly decreased the proliferation of CD8+ T cells." (PMID 38448555, 2024). "Based on the BioGPS database to assess the mRNA levels of 7 hub targets, the hub targets had elevated mRNA levels in lung cancer-related organs, including lung, SmoothMuscle, Cd34+ cells, cd33+ cells and Cd56+ cells." (PMID 39450260, 2024). "Here, we investigated the expression of Siglec receptors on lung cancer patient-derived MDSCs as well as on myeloid cells from healthy donors by gating on CD33+CD11b+HLA-DRlow/- cells." (PMID 38448555, 2024). "We performed flow cytometry to analyze the proportion of CD11b+CD33+HLA-DR− MDSCs in PBMCs from lung cancer patients." (PMID 33717204, 2021). "For lung cancer, the main body of literature reports increases of monocytic CD33+CD11b+CD14+ MDSCs or granulocytic-like CD33+CD11b+CD14− MDSCs." (PMID 32849585, 2020). "To confirm the in vivo promotion of M-MDSC by DEX, we isolated CD11b+CD33+HLA-DR− cells from lung cancer patients after surgery and performed a series of coculture experiments in vitro." (PMID 30537999, 2018). "In the context of surgery, CD11b+CD33+HLA-DR−-expressing MDSC significantly increased in lung cancer patients after thoracotomy and MDSC isolated after surgery from lung cancer patients were more efficient in promoting angiogenesis via VEGF." (PMID 30537999, 2018). "(A, B) CD11b+CD33+HLA-DR− cells (3 × 104 cells/well) isolated from lung cancer patients (n = 6) 24 h after surgery were cocultured with (A) dexmedetomidine (DEX) or (B) dexmedetomidine and yohimbine (DEX + YOH)." (PMID 30537999, 2018). "Here, we demonstrated that the M-MDSCs expressing CD11b+CD33+HLA-DR–CD14+ in lung cancer patients after thoractomy significantly increased in comparison with preoperation, and their accumulation linearly correlated with an increase in Treg." (PMID 28178645, 2017). "Administration of Cucurbitacin B (CuB) to lung cancer patients was shown to decrease the numbers of bona fide MDSCs (Lin− HLA-DR− CD33+), while it increased the numbers of mature Lin- HLA-DR+ CD33+ myeloid cells in peripheral blood." (PMID 27029037, 2016). "Lung carcinoma and glioma cell lines, which had a low frequency of CD33+ MDSC induction, also were found to induce with moderate frequency the CD11b+ MDSC subset." (PMID 21658270, 2011). "In contrast, Hotairm1 expression is decreased in CD33+ MDSCs from patients with lung cancer." (PMID 33335790, 2020). "In addition, DEX increases the number of CD11b + CD33 + HLA-DR-CD14 + M-MDSCs in lung cancer patients after thoracotomy and promotes tumor metastasis by increasing the production of VEGF18." (PMID 32632241, 2020). "DEX increased CD11b+CD33+HLA-DR–CD14+ M-MDSC in lung cancer patients after thoractomy." (PMID 30537999, 2018). "Thus, we isolated CD11b+CD33+HLA-DR−CD14− MDSCs from tumor tissues of lung cancer patients, and qRT-PCR was used to detect the level of HOTAIRM1." (PMID 29662483, 2018). "Based on these surface markers, we found that while CD11b+CD33+HLA-DR− cells (MDSC) circulate in lung cancer patients at baseline (preoperation, T0), the frequency of CD11b+CD33+HLA-DR− cells was significantly increased on postoperative day 1, 3 and 7 (T1, T2 and T3, respectively)." (PMID 30537999, 2018). "To further determine whether RUNXOR was expressed by MDSCs, we isolated CD11b + CD33 + HLA-DR-CD14- MDSCs from tumor and adjacent tissues of lung cancer patients and detected the expression of RUNXOR by using qRT-PCR." (PMID 29914443, 2018).
lung carcinoma (continued). "Transgenic expression of CD33 in lung cancer cells that do not endogenously express CD33 resulted in rapamycin-dependent DARIC-VHH1 T cell proliferation in vitro, whereas targeted deletion of CD33 from CD33+ AML cell lines eliminated IFN-γ responses in vitro and in vivo." (PMID 38502193, 2024).
lymphoma (21 papers, 2016 to 2025). A malignant (clonal) proliferation of B- lymphocytes or T- lymphocytes which involves the lymph nodes, bone marrow and/or extranodal sites. "Six tissues were common to both genes: 721 B lymphoblasts, CD14+ monocytes, CD33+ myeloid cells, Wholeblood, Lymphoma Burkitts (Raji), and Lymphoma Burkitts (Daudi)." (PMID 40395233, 2025). "The expression of myeloid antigens CD13 and CD33 in B-lymphoblastic leukemia/lymphoma is typically observed in B-lymphoblastic leukemia/lymphoma with BCR::ABL1 fusion." (PMID 40227608, 2025). "In one study of 180 pediatric cases of T-lymphoblastic leukemia/lymphoma, myeloid antigens were expressed in 16.3% of cases; most commonly CD33, in 13% of cases, followed by CD13 in 7.1% of cases, with smaller percentages of cases expressing CD14 and CD15." (PMID 40227608, 2025). "Moreover, we acknowledge the fact that the prognostic significance of either CD66b+CD33dimHLA-DR− G-MDSCs or whole blood CD11b+CD33+CD14−HLA-DR− G-MDSCs will be definitely established only by future studies evaluating larger series of lymphoma patients." (PMID 27050283, 2016). "In our study, the most typical tissues were cardiomyocytes, lymphoma Burkitt, CD33+ myeloid, pineal, and Dorsal Root Ganglion, which might imply the probable reasons for clinical manifestations in MDD, such as repeated infection, circadian rhythm disorder and feeling pain." (PMID 36339846, 2022). "Myeloid antigens, including CD13, CD33, and CD15, may be expressed in a minority of cases of T-lymphoblastic leukemia/lymphoma." (PMID 40227608, 2025). "B-lymphoblastic leukemia/lymphoma with IGH::IL3 fusion may show expressions of myeloid markers CD13 and/or CD33." (PMID 40227608, 2025). "Conventional immunotherapy targets for AML such as CD33 and CD123 have been proposed as targets for chimeric antigen receptor (CAR)-engineered T-cells (CAR-T-cells), a therapy that has been highly successful in the treatment of B-cell leukemia and lymphoma." (PMID 29077054, 2017). "B-lymphoblastic leukemia/lymphoma with ETV6::RUNX1 fusion is often negative for CD9, CD20, and CD66c, and positive for myeloid markers CD13 and CD33." (PMID 40227608, 2025). "B-lymphoblastic leukemia/lymphoma may express one or more markers of myeloid lineage, including CD13 and CD33, but is usually negative for moderate to high levels of myeloperoxidase expression (which can be assessed by flow cytometric analysis, cytochemical, or immunohistochemical staining)." (PMID 40227608, 2025).
melanoma (18 papers, 2014 to 2025). A malignant, usually aggressive tumor composed of atypical, neoplastic melanocytes. "Diagnostic tissue from 136 cases of melanoma was evaluated by immunohistochemistry for CD33, VISTA, and PD-1 expression." (PMID 32873829, 2020). "Furthermore, high expression of CD33 was associated with poor clinicopathological variables and was an independent prognostic factor in melanoma." (PMID 32873829, 2020). "Here, we show using humanized mice that colonization of distant visceral organs with melanoma is dependent upon a human CD33+CD11b+CD117+ progenitor cell subset comprising <4% of the human CD45+ leukocytes." (PMID 33857287, 2021). "Single-cell RNA-seq analysis identified a gene signature of a KIT/CD117–expressing CD33+ subset that correlated with decreased overall survival in a TCGA melanoma cohort." (PMID 33857287, 2021). "Colonization of visceral organs with melanoma in humanized NSG-SGM3 mice is dependent upon human CD33+CD11b+CD117+ progenitor cells." (PMID 33857287, 2021). "A gene signature of KIT/CD117–expressing CD33+ subset correlates with decreased overall survival in TCGA melanoma samples and represents a novel candidate biomarker." (PMID 33857287, 2021). "We evaluated correlations among the expression of VISTA, the myeloid-derived suppressor cell marker CD33, and programmed death-1 (PD-1), and determined their relationships with clinicopathological characteristics and disease outcomes in melanoma." (PMID 32873829, 2020). "VISTA and CD33 expression are independent unfavourable prognostic factors in melanoma, which suggests their potential as therapeutic targets." (PMID 32873829, 2020). "Flow cytometric analysis of VEGFR1 in the MDSC fraction of CD11B+ cells (defined as CD11B+ CD14− HLA− CD33+) also revealed elevated protein levels in stage IV melanoma patients compared with controls (unpaired t-test, P<0.001)." (PMID 25924227, 2015). "The few targets we were able to detect on melanoma cells were ErbB3, CD33 and CD44, confirming previous observations." (PMID 24489649, 2014). "In freshly obtained melanoma samples, the percentage of CD33+ cells ranged from 1% to 7%, and in cultured or xenotransplanted melanoma cells, it ranged between 7% and 31%." (PMID 24489649, 2014). "Another cell surface marker found to be differentially expressed on melanoma cells was Siglec-3 (CD33)." (PMID 24489649, 2014). "The degree of infiltration of CD33-positive bone marrow cells may indicate a poor prognosis of patients with melanoma." (PMID 37207210, 2023). "Additionally, we found that monocyte CD33 expression was higher in melanoma patients that responded to anti-PD-1, and CD33 was also associated with better survival in melanoma patients within the TCGA dataset (Supplementary 4C)." (PMID 35493454, 2022). "Double IF staining of melanoma tissue showed that CD33-positive cells also expressed VISTA." (PMID 32873829, 2020). "A highly significant elevation of ID1 was observed in CD33+CD11b+CD14+HLA-DRlow monocytic MDSC in the blood of melanoma patients compared to their HLA-DRhigh counterparts, while expression of ID1 correlated positively with established MDSC markers S100A8/9 and iNOS." (PMID 31953577, 2020). "VISTA expression positively correlated with CD33 expression in melanoma tissue." (PMID 32873829, 2020). "In this study, about 30% of melanoma specimens showed high expression of CD33." (PMID 32873829, 2020). "Interestingly, the gene expression levels of CD33, a marker of myeloid-derived suppressor cells (MDSCs), and IL-10, which is mainly secreted by regulatory T cells (Tregs), were higher in MAP2K1/2-mutated melanoma, compared to those in wild-type melanoma." (PMID 35069558, 2021). "Previously documented markers including FOXP3 (Tregs), CD163 (TAMs), CD33 (TANs), FAP (CAFs), MIA (melanoma), and ALDH1A1 (HNSC), were used for cell-type annotation." (PMID 35812726, 2022).